INS (insulin)
Diseases named in the same sentence as INS in open-access papers (continued):
Sharing a sentence is not in itself a finding about the gene and the disease.
Obesity (continued). "Further evidence highlights how paternal obesity may compromise metabolic regulation in offspring, affecting pathways that control insulin signaling, energy balance, and lipid metabolism." (PMID 39770898, 2024). "In this study, we tested the hypothesis that differences in body composition and insulin sensitivity may explain the patterns of glucose dynamics in T1D patients with overweight/obesity and normal body weight." (PMID 39335526, 2024). "Next, insulin action on lipolysis or lipogenesis was examined in subjects with obesity." (PMID 38491191, 2024). "Enhancing NAFLD management could represent an initial step in the metabolic recuperation from obesity‐related ailments, promoting the restoration of insulin signaling and lipid metabolism." (PMID 38628220, 2024). "Moreover, TNF-α dysfunction was shown to improve insulin sensitivity and glucose homeostasis, solidifying the critical role of this inflammatory response in regulating insulin action during obesity." (PMID 38807790, 2024). "Adiponectin exerts insulin sensitizing and anti-inflammatory effects and is reduced in obesity." (PMID 37934800, 2024). "In addition, the inhibitor of cytokine signaling 3 (SOCS3) and/or protein tyrosine phosphatase 1B (PTP1B) appear to share the suppressive effects on insulin and leptin signalings that are frequently observed in obesity." (PMID 38921683, 2024). "Propionic acid prevents diet-induced obesity and improves insulin sensitivity." (PMID 38930856, 2024). "Owing to IL-6-mediated effects on ATM proliferation, polarization and recruitment, IL-6 and mannose receptor 1 expression sustain potential targets to rescue insulin sensitivity in obesity and the role of IL-6 as a pro-inflammatory clinical parameter should be revised." (PMID 38482013, 2024). "Cortical GU was higher in healthy nonobese controls compared with people with obesity (4.7 [3.4-5.6] vs 3.1 [2.2-4.3], P = .004, respectively), and it associated positively with the degree of insulin sensitivity (M value) (r = 0.42, P = .01)." (PMID 37955868, 2024). "An increase in KA in skeletal muscles could increase thermogenesis in the long term and limit weight gain, insulin resistance and inflammation, also KA presents in breast milk and may act as an anti‐obesity agent in infants." (PMID 38479983, 2024). "Although Ormdl3 was reported to be upregulated in the β-cells of ob/ob mice that spontaneously develop obesity, another study showed that loss of Ormdl3 in β-cells did not alter glucose tolerance or insulin sensitivity." (PMID 38081412, 2024). "Therefore, disruption of insulin signaling in all cells of the NVU of mice with obesity appears to affect multiple cellular processes known to be related to mechanistic disturbance underlying dementia." (PMID 39456952, 2024). "Our results suggest that SFN may be a naturally occurring insulin-sensitizing agent that is capable of improving the metabolic processes in HFD-induced obesity and IR and thereby may be a promising compound for T2D prevention." (PMID 38611359, 2024). "Moreover, our earlier study showed an inverse correlation of iso BCFA with 18:1/18:0 DI, as well as with TG and insulin, in patients with obesity." (PMID 37964164, 2024). "Visfatin, an insulin-mimetic adipokine, can link IR with obesity." (PMID 39045924, 2024). "Below the inflection point, the SII was significantly and positively correlated with BMI, probably reflecting increased levels of inflammatory mediators in the early stages of obesity, which affect insulin sensitivity and fat metabolism and promote fat accumulation." (PMID 39116149, 2024). "In a study comparing glucose turnover in response to a glucagon infusion between lean volunteers and patients with obesity, endogenous glucose production and rate of glucose disappearance were higher at baseline in lean subjects (due to greater insulin sensitivity)." (PMID 38579751, 2024).
Obesity (continued). "Fourth, we did not assess intraoperative and postoperative blood glucose levels, which could have been beneficial for evaluating insulin resistance and altered glycemic responses commonly observed in patients with obesity during the perioperative period." (PMID 38472704, 2024). "Furthermore, obesity in children with impaired insulin secretion will lead to an earlier clinical manifestation of T1DM." (PMID 39099754, 2024). "CTRP6 knockdown inhibited diet-induced obesity and improved insulin sensitivity in mice." (PMID 38791090, 2024). "As such, miR-6236 may regulate other molecules relevant to adipocyte insulin signaling during obesity." (PMID 38918428, 2024). "In addition, future studies are needed to include information on lipoprotein, insulin levels, and waist-hip ratio to elucidate the complex associations between T2DM, obesity, and dementia." (PMID 39535979, 2024). "This is consistent with myocyte studies from healthy insulin-sensitive adults, where lipids are appropriately mobilized and lipid oxidation is higher during 24-hour or 3-day lipid challenge relative to adults with established obesity." (PMID 39226911, 2024). "On the other hand, late chronotype is associated with a decrease in insulin sensitivity and energy expenditure in addition to an increase in glucose, insulin, and triglyceride levels, independent of obesity." (PMID 39744380, 2024). "Finally, we summarize the effects of BCAA supplementation or restriction on obesity and insulin sensitivity." (PMID 39007094, 2024). "In addition, sex, smoking, obesity, and insulin therapy were significantly different among groups (all P for trend < 0.05)." (PMID 38997409, 2024). "These 11-oxygenated androgens have been shown to affect obesity and insulin sensitivity." (PMID 39145114, 2024). "However, also different T-cell populations can affect ATM polarization and proliferation, which in turn affects insulin sensitivity and the outcome of diet-induced obesity." (PMID 38482013, 2024). "Moreover, they also exhibited improved insulin sensitivity and were protected from the development of obesity-related metabolic complications in adulthood, such as liver steatosis, when exposed to the dietary stressor of a high-fat diet." (PMID 38786092, 2024). "Future studies are also needed to evauate whether beneficial weight losss associated with GLP-1ARs is also correlated with improvements in obesity-related cardiometabolic markers such as fasting insulin and FPG, TG, TC." (PMID 38762728, 2024). "In addition, FGF21 can modulate obesity and hepatic metabolic homeostasis via increased energy consumption and insulin sensitivity." (PMID 38891828, 2024). "Additionally, FMT can improve insulin sensitivity in patients with severe obesity and metabolic syndrome." (PMID 39776845, 2024). "There are viruses related to the obesity process, known as obesogenic viruses, among which is Adenovirus 36, which increases insulin sensitivity in adipocytes, generating more significant lipogenesis while reducing the expression and secretion of leptin, thus increasing hunger." (PMID 38473918, 2024). "Recent studies have also revealed anti-obesity effects of dietary resveratrol supplementation, potentially by mimicking the metabolic effects of long-term caloric restriction and improving adipose tissue function and insulin sensitivity in obese model." (PMID 38976215, 2024). "In addition, animal studies lend support for a role of glutathione in counteracting obesity by enhancing insulin sensitivity and promoting lipid degradation." (PMID 39519120, 2024). "However, more studies are required to determine the contribution of HEL on SFA- modulation of insulin responsiveness and inflammatory response, phenomena that become impaired in obesity and throughout the aging process." (PMID 38794136, 2024). "It ameliorates insulin sensitivity and is increased in patients with obesity and DM2." (PMID 39519480, 2024).
Obesity (continued). "Specifically, polyphenols affect insulin, a hormone that is essential for regulating blood sugar, and they also play a role, in part, in a complex web of factors that affect the progression of obesity." (PMID 38397458, 2024). "Furthermore, a statistically significant positive relationship was observed between HAdV-36 seropositivity and insulin levels in the obesity group." (PMID 38932214, 2024). "Moreover, in the context of obesity, butyrate supplementation has been shown to improve insulin sensitivity and decrease adiposity." (PMID 38393013, 2024). "In obesity, however, IR leads to reduced insulin-stimulated glucose transport in adipocytes." (PMID 39337290, 2024). "OPG undergoes a significant increase during obesity progression, and its expression is triggered by high blood sugar and increased insulin levels in adipocytes within visceral fat tissue at the early stages of obesity development, leading to adipocyte enlargement and internal lipid accumulation." (PMID 39335642, 2024). "Obesity and type 2 diabetes affect peripheral insulin signaling and trigger inflammation." (PMID 38945951, 2024). "Therefore, the insulin signaling pathway is also considered as a potential target in obesity treatment." (PMID 38327997, 2024). "Therefore, during pregnancy, obesity-induced insulin resistance decreases adiponectin levels, but also the pro-inflammatory environment and ER stress by inhibiting insulin action in preventing adiponectin ubiquitination." (PMID 39083072, 2024). "We examined the effects of 1 month of a eucaloric, high-fat (48% of calories) diet (HFD) on gonadotropin secretion in normal-weight women to interrogate the role of free fatty acids and insulin in mediating the relative hypogonadotropic hypogonadism of obesity." (PMID 38178979, 2024). "However, PCOS has heterogeneous symptoms that often include obesity, elevated insulin, and/or a diminished capacity for glucose disposal." (PMID 38131197, 2024). "Similarly, the administration of a TGF-β neutralizing antibody (ID11) improves glucose tolerance, insulin sensitivity, body weight gain, and energy balance in both genetic and diet-induced obesity models." (PMID 39171528, 2024). "GIP and GLP-1 dual agonists, such as Mounjaro, enable insulin secretion through activation of β-cell GIP receptors and appear to greatly enhance the satiety and weight loss encountered with GLP-1R activation alone, aiding obesity." (PMID 39519546, 2024). "In addition, there was a strong inverse correlation between BMI and intestinal GU, confirming that intestinal insulin sensitivity is closely related to obesity." (PMID 39458548, 2024). "White kidney bean extract is a promising anti-obesity candidate that controls fat buildup, lowers postprandial plasma hyperglycemia and insulin, and has anorexigenic effects, according to numerous in vivo investigations conducted in both animal and human models." (PMID 38276548, 2024). "These achievements have solved a more than hundred-year-old mystery about the role of the gut in glucose metabolism, identified a new endocrine mechanism regulating insulin secretion and provided the first effective treatment for obesity with profound implications for maintaining human health." (PMID 39297680, 2024). "Numerous mechanisms have been suggested to explain IR induced by obesity, including lipotoxicity, ER stress, mitochondrial dysfunction, oxidative stress, hypoxia, and disruption of the insulin signaling pathway, among which, obesity‐related inflammation emerges as a significant contributor to IR201." (PMID 38812572, 2024). "In fact, Catalano and colleagues observed that women with obesity and GDM had a lower suppression of endogenous glucose production (gluconeogenesis and glycogenesis) during insulin infusion, predisposing these women to a higher risk of developing T2D later in later life." (PMID 39083072, 2024).
Obesity (continued). "Understanding the pathophysiologic relationships between insulin, glycemia, obesity, and inflammation, and how they relate to cancer may help target DM treatment more successfully (Macciò & Madeddu, 2011)." (PMID 38726403, 2024). "Given that insulin sensitivity is a pivotal factor in regulating ovulatory function and fertility in women, attention as regards nutrition should be directed towards patterns that promote insulin sensitivity and glucose metabolism to enhance fertility outcomes in women with obesity and T2DM." (PMID 39006367, 2024). "Obesity and elevated insulin levels generally have a positive impact on BMD." (PMID 38731059, 2024). "In addition, within the context of obesity-associated IR, BITC enhanced insulin sensitivity in a Nrf2-dependent manner, lowering hyperglycemia in vivo and in vitro and potentially protecting against obesity-related T2D." (PMID 39770075, 2024). "White adipose tissue undergoes dynamic changes in obesity, including adipose tissue pathological expansion, hypoxia, adipose tissue fibrosis, immune cells infiltration and finally leads to chronic low‐grade inflammation and insulin resistance." (PMID 38812572, 2024). "This mouse model could also be used to test the efficacy of drugs targeting the signaling pathways altered by obesity, including insulin, leptin, and free fatty acid." (PMID 39201703, 2024). "Preliminary research suggests that obesity may directly impact brain health and function via mechanisms such as pro-inflammatory responses, oxidative stress, insulin resistance, hormonal imbalances, and others." (PMID 38840158, 2024). "Of them, HFD-induced obese mouse model is closer to human MASLD status, characterized by obesity (body weight gain), insulin resistance, intracellular TG accumulation in the liver, hepatocellular fat vacuoles, and elevations in serum levels of ALT, AST, TC, and LDL-c as shown in this study." (PMID 39508046, 2024). "Clinical trials have reported enhancements in metabolic markers following antioxidant interventions, including a study that demonstrated that supplementation with vitamin E notably improved insulin sensitivity and decreased markers of oxidative stress in individuals with obesity and type 2 diabetes." (PMID 38391792, 2024). "In addition, pectic-type polysaccharides such as rhamnogalacturonan-I (RG-I) and homogalacturonan (HG) have demonstrated potential in addressing metabolic disorders, including insulin resistance, inflammation, and diet-induced obesity." (PMID 39683533, 2024). "Obesity is characterized by the excess of body fat and it is distinct from insulin resistance." (PMID 38755663, 2024). "Obesity not only reduces lung capacity and limits lung expansion but also affects blood pressure regulation through various mechanisms, including changes in hormone activity (such as insulin resistance and abnormal adipokine secretion)." (PMID 38962763, 2024). "Accordingly, upregulation of CAT may promote insulin sensibility and protect against obesity by influencing energy expenditure processes." (PMID 38703299, 2024). "Thus far, there are few reports regarding potential effects of SerpinA1 on metabolism, although SerpinA1 has been shown to inhibit obesity-induced neutrophil elastase and improve insulin sensitivity." (PMID 39532838, 2024). "Our findings suggest that adipose tissue eosinophils may play a role in regulating body fat, thereby reducing insulin, which is a mediator of obesity-related airway hyperresponsiveness." (PMID 39316677, 2024). "The increased expression of autophagy-related genes correlates with the degree of visceral fat mass obesity, and adipocyte hypertrophy and autophagy in adipose tissue are associated with impaired glucose tolerance in a manner independent of BMI and insulin." (PMID 39683397, 2024). "Due to the negative health consequences of obesity in horses, many studies have investigated the effects of either diet and/or exercise on weight loss and insulin dynamics in horses." (PMID 38473112, 2024).
Obesity (continued). "Interestingly, both Mlkl−/− and Mlkl+/− mice displayed resistance to HFHFrHC diet-induced obesity and improved insulin sensitivity compared to control wild-type mice (WT, Mlkl+/+) fed the same diet." (PMID 38474061, 2024). "However, GLN has also demonstrated contradictory effects, such as reducing BW gain and liver weight and mitigating obesity-induced insulin resistance and impaired insulin signaling in the liver." (PMID 38673797, 2024). "Increased inflammation exhibited a low level of Turicibacter and a high level of Lactococcus, all of which suggest that the development of obesity may result from the alteration of gut microbiome via increasing systemic inflammation and insulin resistance." (PMID 37927197, 2024). "Moreover, the obesity-related phenotypes observed in ShSCT mice, such as glucose intolerance and insulin insensitivity, were consistently reproduced in SCTVMH−/− mice." (PMID 38310104, 2024). "P2Y6R knockout mice are also protected against diet-induced obesity, having improved glucose tolerance and insulin sensitivity with reduced systemic inflammation, suggesting that P2Y6R antagonists might be used for treatment of obesity and type 2 diabetes." (PMID 39243044, 2024). "In addition, human and animal studies have shown that pharmaceutical chaperones, which are small molecules designed to stabilize the folding of proteins, improve insulin sensitivity in subjects with obesity." (PMID 38703299, 2024). "In addition to the effects of dietary fibre on cardiovascular health, many studies have focused on the relationship between carbohydrates on blood glucose, diabetes and obesity and have proposed a carbohydrate-insulin model." (PMID 38799425, 2024). "Studies reporting such evidence indicate common pathways linking obesity to mental disorders, including genetic influence, obesity biomarkers (insulin resistance, inflammatory processes, oxidative damage), environmental factors (alcohol use, physical inactivity, socioeconomic status), and distress." (PMID 39420888, 2024). "Terms with greatest strength are the following: Age at assessment: strength = 1.70, fdr = 2.91E-05; Insulin measurement: strength = 1.63, fdr = 7.25E-15; Obesity: strength = 1.50, fdr = 0.044; Birth weight: strength = 1.41, fdr = 7.04E-07; Glucose measurement: strength = 1.34, fdr = 5.25E-17." (PMID 39687027, 2024). "In addition to other antagonists, specific CCR2 antagonists have shown efficacy in reducing blood glucose and enhancing insulin sensitivity in obesity treatments." (PMID 39334887, 2024). "In conclusion, dietary n-3 and n-6 PUFAs may be a useful strategy to modulate macrophage–myocyte inflammatory crosstalk and improve myocyte insulin sensitivity in obesity." (PMID 38999834, 2024). "Obesity-related metabolic disorders, such as insulin resistance and lipid metabolism dysregulation, may further exacerbate lung inflammation through complex biological signaling pathways, contributing to the development of emphysema." (PMID 39584854, 2024). "It is crucial to develop treatments that enhance and restore pancreatic islet function without causing excessive insulin secretion or contributing to obesity." (PMID 39275180, 2024). "Additionally, Etv5 is considered a transcriptional suppressor of insulin secretion related to obesity and a novel transcription factor involved in regulating hepatic fatty acid metabolism." (PMID 39840059, 2024). "After the initial 10 weeks WD feeding, LCHF diet demonstrated effectiveness in halting weight gain, maintaining a normal glucose tolerance and insulin levels, in comparison to the WD-fed mice, which developed obesity, glucose intolerance, increased insulin levels and induced NAFLD." (PMID 38571752, 2024). "Furthermore, resveratrol has demonstrated the ability to alleviate obesity-induced up-regulation of inflammatory cytokines and improve insulin signaling in adipose tissue." (PMID 38732542, 2024).